TNF (tumor necrosis factor)
Diseases named in the same sentence as TNF in open-access papers (continued):
Sharing a sentence is not in itself a finding about the gene and the disease.
hemorrhagic fever with renal syndrome (2 papers, 2008 to 2012). A viral infectious disease that is a hemorrhagic fever, located_in kidney, has_material_basis_in Hantaan virus, has_material_basis_in Dobrava-Belgrade virus, has_material_basis_in Seoul virus, or has_material_basis_in Puumala virus, which are carried and transmitted_by rodents. "Since TNF-α is involved in the pathogenesis of hantavirus-caused hemorrhagic fever with renal syndrome (HFRS) we investigated its effects on HFRS-causing hantavirus-infected cells." (PMID 18822184, 2008). "TNF-α is also correlated with the severity of hemorrhagic fever with renal syndrome (HFRS)." (PMID 22911786, 2012).
hemorrhoid (2 papers, 2024 to 2025). Dilated veins in the anal canal. "In total, 2 factors were among the 5 most important in 2 models: TNF-α in DT and NB models and hemorrhoids in LR and ANN models." (PMID 40311089, 2025). "Using the combined dataset, new factors emerged as the primary predictors of mesh exposure: IL-8, tumor necrosis factor-α, and the presence of hemorrhoids." (PMID 40311089, 2025). "Inflammatory cytokines and enzymes, such as interleukin-6 (IL-6), interleukin-17 (IL-17), tumor necrosis factor-alpha (TNF-α), nitric oxide (NO), inducible nitric oxide synthase (iNOS), and matrix metalloproteinases (MMPs), show a high correlation with the pathogenesis of hemorrhoids." (PMID 38893547, 2024). "Significantly reduces the level of TNF-α, VEGF, and capillary permeability in the mucosa; may have hemorrhoid improvement effect." (PMID 38893547, 2024).
Hip dysplasia (2 papers, 2016 to 2022). The presence of developmental dysplasia of the hip. "Several studies found that the concentration of TNF-α in SF was significantly higher in joints with OA secondary to hip dysplasia or cruciate ligament rupture compared to healthy joints." (PMID 35720854, 2022). "As expected, low TNF-α, IL-1β and IL-6 expression levels were obtained in normal hip dysplasia tissues and in tissues after mechanical loosening." (PMID 26004143, 2016).
histiocytic sarcoma (2 papers, 2021 to 2026). An aggressive malignant neoplasm with a poor response to therapy, usually presenting as stage III/IV disease. "Candidate genes at both loci, PIK3R6 and TNFAIP6, have tumor suppressive and metastatic roles in other cancers, and mutations in members of the PI3K and tumor necrosis factor pathways have been identified in human histiocytic sarcoma and lymphoma tumors." (PMID 33983928, 2021). "C-C motif chemokine ligand 3 (CCL3) was strongly correlated with tumor necrosis factor-alpha (TNF-α) secretion exclusively in histiocytic sarcoma cells, and recombinant CCL3 induced dose-dependent TNF-α secretion from macrophages." (PMID 42030266, 2026).
hydrocele (2 papers, 2012 to 2025). "The presence of inflammatory mediators, such as interleukins (IL-1, IL-6) and tumor necrosis factor-alpha (TNF-α), has been noted in the fluid of hydroceles, suggesting an underlying inflammatory component that can influence hydrocele formation and maintenance." (PMID 40137708, 2025). "Other studies have linked TNF with promoting the production of vascular endothelial growth factors such as VEGF-C and VEGF-A, which reportedly contribute to the development of lymphodema and hydrocele." (PMID 22509424, 2012).
hydronephrosis (2 papers, 2017 to 2018). Collection of urine in the renal pelvis that results in dilatation of the renal pelvis and calyces. "TCDD-induced hydronephrosis was more severe in wild-type fetuses than in cPLA2α-null fetuses regardless of sex, and kidney expression levels of the inflammatory cytokines interleukin-1β and tumor necrosis factor-α were increased in a cPLA2α-dependent manner in TCDD-exposed fetuses." (PMID 29043426, 2018).
hyper-IgE syndrome (2 papers, 2015 to 2017). A condition that is characterized by elevated serum IgE, dermatitis, and respiratory infections. "Further underscoring its role in human disease, dominant autosomal STAT3 mutations account for numerous symptoms in Hyper-IgE syndrome (HIES) patients such as misregulated TNFα levels and scoliosis." (PMID 28222105, 2017). "The STAT3 DNA binding domain (DBD, 320–494) mutation in hyper immunoglobulin E syndrome (HIES), called the HIES mutation (R382Q, R382W or V463Δ), which elevates IgE synthesis, inhibits SIE binding activity and sensitizes genes such as TNF-α for expression." (PMID 26384563, 2015).
hyper-lipemia (2 papers, 2018 to 2024). "The tumor necrosis factor (TNF) increases the fat decomposition, resulting in the increase of the level of the cyclic free fatty acid, which stimulates the production of triglycerides of the liver, which causes TNF-induced hyperlipemia." (PMID 38808035, 2024).
Hypernatremia (2 papers, 2022 to 2023). An abnormally increased sodium concentration in the blood. "In the current study, day 1 G-CSF and TNF-α responses after LPS stimulation were significantly lower in the hypernatremia group than in the eunatremia group." (PMID 36140385, 2022). "The hypernatremia group demonstrated higher day 1 G-CSF and TNF-α responses than the eunatremia group (p = 0.019 and 0.046, respectively)." (PMID 36140385, 2022). "Because the hypernatremia group demonstrated G-CSF and TNF-α downregulation, as well as a lower HLA-DR-expressing monocyte percentage, the potential for immune paralysis should be considered." (PMID 36140385, 2022). "The higher mortality in patients with hypernatremia on admission was possibly related to the downregulation of G-CSF and TNF-α secretion after endotoxin stimulation." (PMID 36140385, 2022). "With regard to the ICU-acquired hypernatremia, an upregulation of day 3 G-CSF and TNF-α release was observed, suggesting that patients with acquired hypernatremia demonstrate a hyperinflammatory status." (PMID 36140385, 2022). "However, compared with patients with sustained eunatremia, those with acquired hypernatremia had significantly higher day 3 G-CSF and TNF-α responses (p = 0.049 and 0.009, respectively)." (PMID 36140385, 2022). "Day 1 granulocyte colony-stimulating factor (G-CSF) and tumor necrosis factor (TNF) α levels were relatively low in patients with hypernatremia (p = 0.020 and 0.010, respectively) but relatively high in patients with acquired hypernatremia (p = 0.049 and 0.009, respectively)." (PMID 36140385, 2022). "Therefore, G-CSF and TNF-α release might be downregulated in patients with hypernatremia." (PMID 36140385, 2022).
hyperplasia (2 papers, 2022 to 2025). An abnormal increase in the number of cells in an organ or a tissue with consequent enlargement. "Leukocyte-derived cytokines, including TNF-α, were reported to be potent inducers of epidermal growth factors (EGF) and receptor (EGFR), which attributed to epidermal hyperplasia and thickening in chronic skin disorders." (PMID 36204219, 2022).
hyperprolactinaemia (2 papers, 2017 to 2022). "This study aimed to investigate the effects of anti-tumor necrosis factor (TNF)-α antibody (Ab) on alteration of penile structure in the hyperprolactinemia (hyperPRL) rat model." (PMID 28763467, 2017).
hypertensive heart disease (2 papers, 2021 to 2024). Abnormal enlargement of the heart resulting from long-standing hypertension. "Hypertensive heart disease rats treated with AS-IV (40 mg/kg) or fosinopril had significantly down-regulated IL-6 and TNF-α expression levels compared with the LN group." (PMID 34803698, 2021). "The findings of the PPI network indicated that IL-6, TNF, IL-1β, and NFKBIA were predicted as the main genes of AS-IV against hypertensive heart disease and the KEGG pathways analysis showed that TNF signaling pathway was its key pathway." (PMID 34803698, 2021). "Our findings indicated that the targeted genes of AS-IV against hypertensive heart disease are involved in oxidative stress and inflammation, including SOD2, SOD1, IL-6, TNF, and IL-1β." (PMID 34803698, 2021).
hypohidrotic ectodermal dysplasia (2 papers, 2016 to 2019). A genetic disorder of ectoderm development characterized by malformation of ectodermal structures such as skin, hair, teeth and sweat glands. "Recent advances in understanding the molecular events underlying hypohidrotic ectodermal dysplasia (HED) caused by mutations of the genes encoding proteins of the tumor necrosis factor α (TNFα)-related signaling pathway have been presented." (PMID 26294279, 2016). "Defects in genes such as EctodysplasinA1 (EdaA1) (tumor necrosis factor [TNF] ligand; Tabby), Edar (TNF receptor; Downless), and Edaradd (death domain adaptor; Crinkled) lead to severely abnormal cusps and molar teeth in mice and hypohidrotic ectodermal dysplasia (HED) in human." (PMID 31109359, 2019).
Hypokalemia (2 papers, 2013 to 2025). An abnormally decreased potassium concentration in the blood. "Additionally, prolonged hypokalemia affects the proliferation and differentiation of T cells and monocyte-macrophages, as well as the expression of pro-inflammatory cytokines such as IL-1β, IL-6, and TNF-α." (PMID 40783707, 2025).
hypoparathyroidism (2 papers, 2021 to 2023). Hypoparathyroidism is an endocrine disorder in which the parathyroid glands in the neck do not produce enough parathyroid hormone (PTH). "In addition, TNF-α and GM-CSF gene expression and circulating TNF-α levels were shown to be decreased in patients with chronic postsurgical hypoparathyroidism, whereas absolute numbers of total CD3−CD56+ natural killer cells were significantly increased." (PMID 37180074, 2023).
hypophysitis (2 papers, 2022 to 2025). Inflammation of the pituitary gland. "We assume that the risk of hypophysitis is the result of toxicity due to treatment with CTLA-4 inhibitor, and we represent the level of toxicity by the concentration of TNF-α in the tumor." (PMID 36355837, 2022). "However, we are unable to fit a lower threshold of TNF-α with exact percentage of patients that will develop hypophysitis." (PMID 36355837, 2022). "The mechanism that leads from toxicity to hypophysitis was not considered, and the level of toxicity, by TNF-α, was taken only within the tumor." (PMID 36355837, 2022).
idiopathic inflammatory myopathies (2 papers, 2015 to 2025). "In our in vitro studies, the highest expression of NKG2D ligands was observed under combined IFNγ and TNFα treatment, two cytokines highly abundant in the muscle microenvironment of idiopathic inflammatory myopathies." (PMID 26646698, 2015).
infectious peritonitis (2 papers, 2008 to 2012). Inflammation of the peritoneum due to infection by bacteria or fungi. "PMφ from CAPD patients collected during infectious peritonitis, showed a marked increase in the secretion of TNFα and IL-1β as compared with macrophages from infection free patients, when they were stimulated ex vivo with LPS." (PMID 22481867, 2012). "In the effluent from patients with infectious peritonitis, as compared with uninfected patients, increased levels of various pro-inflammatory cytokines were found, including IL-1β, IL-8, TNFα, IL-6, and IFNγ." (PMID 22481867, 2012). "TNFα mediated reduction of lymphocytes also reported in disease like Feline infectious peritonitis, African swine fever, HIV etc." (PMID 18937835, 2008).
inner ear disease (2 papers, 2019 to 2024). "Another potential anti-inflammatory therapy for inner ear disorders is the use of TNF-α inhibitors, such as etanercept or infliximab." (PMID 39452111, 2024). "However, the use of TNF-α inhibitors in human inner ear disorders is still limited, and more clinical trials are needed to evaluate their safety and efficacy." (PMID 39452111, 2024).
internal carotid artery stenosis (2 papers, 2014 to 2015). Carotid stenosis is a narrowing or constriction of the inner surface (lumen) of the carotid artery, usually caused by atherosclerosis. "The presence of some cytokins (FGF, TGF-β, and TNF-α) within atheromatic plaque of the internal carotid artery stenosis may accelerate the development of atheromatic plaque and its destabilisation." (PMID 25128019, 2014).
intestinal tuberculosis (2 papers, 2015 to 2020). A tuberculosis that involves the intestine. "In particular, active intestinal tuberculosis must be eliminated when using tumor necrosis factor (TNF) inhibitors." (PMID 32377946, 2020).
iridocyclitis (2 papers, 2021 to 2024). "Similarly, in iridocyclitis, elevated levels of TNF-α and IL-6 in the aqueous humor suggest a role in ocular inflammation." (PMID 39612419, 2024).
lateral epicondylitis (2 papers, 2022 to 2025). inflammation of the lateral epicondyle. "In patients with lateral epicondylitis and shoulder and Achilles tendinopathy, Tendisulfur® supplementation for 60 days led to a drop in VAS, possibly due to the downregulation of NF-κB, TNF-α and IL-6." (PMID 35329992, 2022).
lipoma (2 papers, 2019 to 2021). A benign, usually painless, well-circumscribed lipomatous tumor composed of adipose tissue. "There are no data for isolated LDSCs but it has been shown that IL6 and TNF are up-regulated in lipoma tissue compared to adipose tissue, which is probably due to the presence of various immune cells within the tissue." (PMID 30987193, 2019).
liver neoplasm (2 papers, 2023 to 2024). Tumors or cancers of the LIVER. "A dose of NDEA of 200 mg/kg has been reported to induce liver tumors and could incite chronic inflammation, elevating levels of interleukin-1β (IL-1β), interleukin-6 (IL-6), and tumor necrosis factor-α (TNF-α), and thereby attracting immune cells to the liver tissue." (PMID 37759689, 2023).
Long bone fractures (2 papers, 2023 to 2024). "Long bone fractures increase peripheral serum levels of pro-inflammatory cytokines and hormones (e.g., TNF-α, interleukin-1, growth factor), which pertain to the bone healing response but are also capable of deteriorating TBI pathophysiology and worsening patient’s outcome." (PMID 37297997, 2023).
low grade glioma (2 papers, 2018 to 2022). A grade I or grade II glioma arising from the central nervous system. "scRNA-seq of GBM and low-grade gliomas (LGGs) has revealed that TAMs co-express canonical markers associated with antitumor and tumor-supportive macrophage polarization, with 66% of examined GAMs expressing both the immunosuppressive marker IL-10 and the pro-inflammatory marker TNF-α." (PMID 35784281, 2022).
Löfgren’s syndrome (2 papers, 2015 to 2023). "Some HLA, MHC2TA, BTNL2, CCR2, CCR5, TNF, and ANXA gene polymorphisms are associated with an acute presentation of sarcoidosis—Lofgren’s syndrome, whereas other polymorphisms in these genes are implicated in non-Lofgren’s syndrome." (PMID 37511027, 2023).
lung tumor (2 papers, 2018 to 2024). "Accordingly, EGFR and COX-2/TNF-α activation/induction is expected to play important roles in MGL deficiency-driven lung tumors." (PMID 29348400, 2018).
lymphoid neoplasm (2 papers, 2024). A neoplasm composed of a lymphocytic cell population which is usually malignant (clonal) by molecular genetic and/or immunophenotypic analysis. "On the other hand, in MSCs derived from lymphoid neoplasms, a remarkable number of genes involved in inflammatory processes like the TNF signaling pathway or the NFKB signaling pathway were observed." (PMID 38893194, 2024).
lysosomal disorder (2 papers, 2023 to 2024). "Chronic stimulation of the immune system is a hallmark of many lysosomal disorders, including GD, and it is characterized by a markedly elevated level of proinflammatory cytokines, such as Interleukin-1β (IL-1β), Tumor Necrosis Factor- α (TNF-α), and/or Interleukin-6 (IL-6), and chemokines." (PMID 37446383, 2023).
macular degeneration (2 papers, 2021 to 2025). Loss of vision in the central portion of the retina (macula), secondary to retinal degeneration. "In addition, the levels of proinflammatory cytokines such as IL-1β and TNF-α were increased in patients with macular degeneration, indicating chronic inflammatory diseases." (PMID 40837366, 2025).
major depressive episode (2 papers, 2020 to 2023). "Furthermore, TNF-α could affect blood–brain barrier permeability and CLDN5 expression of endothelial cells in major depressive episodes." (PMID 38111702, 2023).
meconium aspiration syndrome (2 papers, 2015 to 2022). A serious condition in which a newborn breathes a mixture of meconium (the first intestinal discharge) and amniotic fluid into the lungs around the time of delivery. "Meconium aspiration syndrome increased TNFα levels in lung tissue, which was significantly reduced in MAS + CBD piglets." (PMID 35733813, 2022). "The pro-inflammatory cytokines IL-6 and TNFα are secreted to the tracheal aspirate fluid of infants with meconium aspiration syndrome." (PMID 25885541, 2015).
memory (2 papers, 2024 to 2025). The activities involved in the mental information processing system that receives (registers), modifies, stores, and retrieves informational stimuli. "Zeaxanthin and lutein prevented memory impairment more effectively than the positive-control resveratrol by suppressing acetylcholinesterase activity, lipid peroxidation, and pro-inflammatory cytokines (TNF-α, IL-1β)." (PMID 39337316, 2024).
metastatic colorectal cancer (2 papers, 2019 to 2025). "Genetic alteration of TNF associates with MAFLD, showing that SNVs of the TNF gene were frequently found in metastatic colorectal cancer patients whose livers are MAFLD." (PMID 38874196, 2025). "In particular, tumor necrosis factor-α (TNF-α) has been shown to cause a dysfunction in the APC system, resulting in acquired APC resistance and increased VTE risk in metastatic colorectal cancer (mCRC) treated with chemotherapy." (PMID 30650562, 2019).
methicillin-resistant Staphylococcus aureus (2 papers, 2020 to 2024). "Silencing macrophage DRP1 decreased mitochondrial fragmentation and TNF-α production upon stimulation with lipopolysaccharide (LPS) or methicillin-resistant Staphylococcus aureus (MRSA) infection." (PMID 33520735, 2020).
microscopic colitis (2 papers, 2013 to 2023). Inflammation of the colon that is only apparent by microscopic examination. "In those with microscopic colitis, systemic glucocorticoid use as well as second line immune suppression with tumor necrosis factor (TNF) inhibition was lower, as oral budesonide was effective at controlling symptoms in most patients." (PMID 37475035, 2023). "Using molecular techniques it was reported that in patients with microscopic colitis increased IFN-γ, TNF-α, and IL-1β levels suggest a Th1 cytokine profile being involved in the inflammatory process." (PMID 23691336, 2013).
microscopic polyangiitis (2 papers, 2021 to 2025). Microscopic polyangiitis (MPA) is an inflammatory, necrotizing, systemic vasculitis that affects predominantly small vessels (i.e. small arteries, arterioles, capillaries, venules) in multiple organs. "Rituximab is a chimeric anti-CD20 mAb approved for the treatment of anti-TNFα non-responsive RA, Granulomatosis with Polyangiitis (GPA) and Microscopic Polyangiitis (MPA) and is used off-label in some situations such as refractory immune thrombocytopenia and lupus nephritis." (PMID 34122062, 2021).
Middle ear cholesteatoma (2 papers, 2007 to 2020). "The aim of this paper is to analyze the importance of tumor necrosis factor alpha (TNF-α) in bone resorption and its action in acquired middle ear cholesteatoma based on a review and an analysis of literature." (PMID 17505610, 2007). "Middle ear cholesteatoma stem cells (ME-CSCs) showed a significantly increased expression of TLR4 accompanied by a significantly enhanced LPS-dependent pro-inflammatory gene expression pattern of TNFα, IL-1α, IL-1ß, IL-6, and IL-8 compared to non-pathogenic control cells." (PMID 31947538, 2020).